EGFR (epidermal growth factor receptor)
Diseases named in the same sentence as EGFR in open-access papers (continued):
Sharing a sentence is not in itself a finding about the gene and the disease.
cancer (continued). "Subsequently, the synthesized compounds were evaluated for their antiproliferative efficacy against a varied panel of human cancer cell lines, which exhibited different levels of target protein (EGFR and HER2) expression." (PMID 40732338, 2025). "The cancer cells undergo transformation to a reversible drug‐tolerant persister (DTP) state prior to the development of resistance against EGFR‐tyrosine kinase inhibitors (TKIs)." (PMID 40479551, 2025). "EGFR TKIs are developed to target this “addictive” signaling and disrupt the downstream pathways to selectively kill cancer cells." (PMID 40346640, 2025). "Many common driver mutations in cancer, such as RAS- and EGFR-activating mutations, activate downstream cell signaling and converge on the same metabolic pathways to drive unrestricted growth." (PMID 39796781, 2025). "Lapatinib is a dual TKI that exerts its anti-cancer activity primarily through the inhibition of both the EGFR and the HER2." (PMID 40346640, 2025). "Meanwhile, epidermal growth factor receptor (EGFR, also known as HER1 and ErbB1) is one of the earliest receptor tyrosine kinases (RTKs) recognized as anti-cancer targets." (PMID 41008250, 2025). "• Epidermal growth factor receptor (EGFR) and human epidermal growth factor receptor 2 (HER2/neu): MIONPs targeted to the epidermal growth factor receptor (EGFR) have shown promising applications in cancer therapy and imaging." (PMID 40255989, 2025). "In summary, Hub-EGFR.Sig can be used as a predictive biomarker for cancers despite the heterogeneity in various tumors." (PMID 40574864, 2025). "These therapeutic approaches suggest that blocking AREG activity can restore sensitivity to EGFR-targeted therapies in multiple cancer types including colorectal cancer, lung cancer, and pancreatic cancer." (PMID 40725192, 2025). "Acneiform eruptions are common dermatological side effects of cancer therapies, particularly TKIs and EGFR inhibitors, and can significantly impair patients’ quality of life." (PMID 40688897, 2025). "MUC1 interacts closely with EGFR, which promotes cancer progression and influences therapeutic responses, significantly impacting the pathology NSCLC." (PMID 40655139, 2025). "Quinazolinone derivatives are integral to developing EGFR inhibitors for cancer therapy, with their efficacy shaped by specific structural features and SARs." (PMID 40001513, 2025). "The combination of the three will greatly enhance the cytotoxicity of NK cells against cancer cells overexpressing EGFR or ErbB2." (PMID 40859900, 2025). "In cancer research, molecular docking can predict the affinity of anticancer compounds for critical receptors overexpressed in tumors, such as the epidermal growth factor receptor (EGFR) and human epidermal growth factor receptor 2 (HER2)." (PMID 40136447, 2025). "The liposomal nano-platform exhibited fewer toxicity against normal human fibroblasts and elevated proapoptotic effect and toxicity against EGFR-overexpressing cancer cells." (PMID 39891180, 2025). "The ability of SYVN1 to modulate EGFR localization and activity presents a unique mechanism by which cancer cells can evade therapeutic interventions." (PMID 40877231, 2025). "Among these, they identified MCLA-158, an EGFR × LGR5 bispecific antibody, that selectively degraded EGFR in LGR5+ cancer stem cells while sparing healthy tissues." (PMID 40843351, 2025). "Drug resistance and adverse effects are significant challenges in the treatment of cancers targeting the epidermal growth factor receptor (EGFR)." (PMID 40002679, 2025). "In previous experiments, compared with unconjugated siRNAs, GE11-conjugated siRNAs showed an approximately 15-fold increase in uptake by EGFR-expressing cancer cells, likely due to receptor-mediated endocytosis." (PMID 40762837, 2025).
cancer (continued). "EMT, a process regulated by cytokines and epigenetic factors, plays a critical role in cancer metastasis and the development of acquired resistance to EGFR‐TKI." (PMID 40856433, 2025). "This emphasizes the efficiency of using a combination treatment of melittin peptides and gefitinib in patients with wild-type EGFR but EGFR-independent cancers." (PMID 40141140, 2025). "Dysregulation of EGFR and its downstream signaling pathways has long been considered essential regulators of cancer progression." (PMID 40940319, 2025). "By conjugating cetuximab to quaternized starch (Q‐starch) complexed with the siRNA, an increased specificity is achieved toward cancer cells overexpressing the epidermal growth factor receptor (EGFR)." (PMID 40666030, 2025). "Significant molecular functions include kinase activity and small molecule binding, with KEGG pathways noting the PI3K-Akt signaling pathway, EGFR inhibitor resistance, and cancer-related proteoglycan and microRNA pathways." (PMID 40963691, 2025). "The expression perturbation results of hub PPMEs between normal and cancer samples revealed that hub PPMEs were significantly different between normal and cancer samples, except EGFR, LCK, and YES1, and they had higher expression levels in cancer samples." (PMID 39940833, 2025). "This activation is initiated by the binding of epidermal growth factor (EGF) to the extracellular domain of EGFR, which is also the target region of cancer drugs like Cetuximab." (PMID 40332084, 2025). "By inhibiting EGFR signaling, these TKIs prevent cellular proliferation and survival, hindering the progression of cancer." (PMID 40943615, 2025). "Previous studies have reported several mechanisms by which amlodipine inhibits cancer progression, including suppression of PD-L1 expression, inhibition of EGFR activity, and induction of cell cycle arrest in several cancer types." (PMID 41145413, 2025). "Based on a meta-analysis of published cohorts, the overall incidences of VTE with ALK, ROS1, EGFR, and wildtype cancers are 41%, 30%, 12%, and 14%, respectively." (PMID 39858040, 2025). "This review outlines a novel approach to cancer-targeted therapy by focusing on the inhibition of the EGFR kinase domain." (PMID 41488515, 2025). "In epithelial cells, rafts dysregulation contributes to aberrant EGFR activation and resistance to tyrosine kinase inhibitors (TKIs) across cancer types." (PMID 41369325, 2025). "Subsequently, the interaction analysis of scRNA-Seq and bulk RNA-Seq in pan-cancer identified EGFR.Sig and confirmed this phenomenon." (PMID 40574864, 2025). "The study reported that FFJ-5 downregulates PKM2, the epidermal growth factor receptor (EGFR), and the Akt-mediated signaling pathway, and also reduces the production of ATP in cancer cells, leading to energy starvation." (PMID 41465430, 2025). "Several research studies demonstrate that EGFR overexpression correlates with cancer cell differentiation and migration." (PMID 40840553, 2025). "Among proteins enriched in these differentially activated pathways between cancer and normal cells, EGFR was frequently presented." (PMID 39781456, 2025). "Emerging evidence also shows that intrinsic factors, such as altered metabolism, autophagy, cancer stem cells (CSCs), and epithelial–mesenchymal transition (EMT), are associated with poor outcomes despite anti-EGFR mAb treatment." (PMID 40002260, 2025).
cancer (continued). "As an unexpected mechanism, agrin provided ECM‐stiffness cues that activated both wild‐type and mutant EGFR, sustaining its proliferative capabilities in cancer cells." (PMID 40165020, 2025). "A breakthrough came with the identification of mutations in the epidermal growth factor receptor (EGFR), heralding a new era of personalized cancer treatment." (PMID 40003951, 2025). "Lamellipodin is involved in clonogenic radiation survival and cell proliferation, which underscores its complex role in EGFR signaling and its potential as a therapeutic target in cancer treatment." (PMID 40565099, 2025). "Given the critical involvement of TAMs in cancer progression and response to EGFR-targeted therapies, we sought to assess the role of TAMs in combined effects of FMD and gefitinib." (PMID 40808689, 2025). "This implicated the potentiating role of EGFR and, in particular, EGFR(Y1068) in CAP-primed cancer cell death as well as the diagnostic and therapeutic values of this phosphorylation site." (PMID 39781456, 2025). "Inflammatory cytokines such as IL8 and IL1B have been reported to promote resistance to anti-EGFR therapies in other cancers such as colorectal cancer." (PMID 40560045, 2025). "Study has suggested that BF shows strong antitumor effect in cancers with high wild-type EGFR expression." (PMID 40883741, 2025). "Prior studies indicate that ER stress compromises DSB repair, increasing chemosensitivity, while EGFR blockade induces ER stress in cancer cells." (PMID 40830980, 2025). "This was because DDOST affects a process called N-glycosylation, which is crucial for the activity of proteins such as EGFR and PD-L1 involved in cancer growth and immune evasion." (PMID 41413687, 2025). "RTK, including human epidermal growth factor receptor 2 (HER2), vascular endothelial growth factor receptor (VEGFR), and EGFR, can be overexpressed or upregulated in cancer cells." (PMID 40490812, 2025). "Inhibiting EGFR can significantly alter cancer cell metabolism, such as decreasing glycolysis and increasing glutamine utilization, and induce the expression of genes associated with patient survival." (PMID 41226554, 2025). "Based on the ICP-MS results, the B4C anti-EGFR nanoparticles were the least effective in delivering boron to cancer cells." (PMID 40438187, 2025). "Combining EGFR pathway inhibition with an LGR5-targeted approach more effectively treats cancer growth in a wide range of preclinical murine and human model systems." (PMID 40427162, 2025). "Its potential roles in LUAD include curbing cancer cell growth, inhibiting invasion and metastasis, influencing epidermal growth factor receptor (EGFR)-mutant cancers, and synergizing with other therapies." (PMID 40302794, 2025). "MIG-6 can selectively target activated epidermal growth factor receptor (EGFR) and act as an EGFR feedback inhibitor, which indicates its critical role in human cancers." (PMID 40535815, 2025). "Its inhibitory effect on cell growth and clonogenic activity is not only concentration-dependent, as expected, but also depends on the EGFR density of the analyzed cancer cell lines highlighting the in vitro target specificity of this sdAb-based TAT strategy." (PMID 40536585, 2025). "AREG, a ligand of the EGFR, plays a crucial role in promoting cancer cell proliferation, survival, angiogenesis, invasion, metastasis, and the development of drug resistance." (PMID 40725192, 2025).
cancer (continued). "Determining epidermal growth factor receptor (EGFR) gene alterations facilitates assessments of cancer progression and the effectiveness of therapies." (PMID 39789283, 2025). "A dual therapeutic approach combining afatinib with either C9 or CsA has demonstrated a more robust inhibition of the CypA/CD147/EGFR axis, resulting in enhanced suppression of cancer cell proliferation and tumorsphere formation." (PMID 41479915, 2025). "Kyoto Encyclopedia of Genes and Genomes enrichment analysis highlighted cancer signaling pathways, including epidermal growth factor receptor (EGFR)." (PMID 40391080, 2025). "Although EGFR signaling has been reported to induce the EMT in cancers, LUAD cells harboring constitutively active EGFR mutations tend to display epithelial characteristics compared to those with WT EGFR." (PMID 40429751, 2025). "Taken together, the EGFR.Sig predictive models developed with the logistic regression algorithm can effectively predict the response of cancer patients to immunotherapy." (PMID 40574864, 2025). "Due to its involvement in the development of cancer and its potential as a prognostic factor, EGFR is the receptor tyrosine kinase that has been studied in various studies." (PMID 39886047, 2025). "GNP-EGFR specifically binds to cells with high EGFR expression, making it a powerful tool for distinguishing malignant tumors." (PMID 40095737, 2025). "It is necessary to explore the TME of EGFR‐related cancers, study its changes after TKI treatment, and the resulting downstream physiological changes." (PMID 40859900, 2025). "Our research summarizes the best evidence for the management of epidermal growth factor receptor inhibitors (EGFRI)-induced skin toxicity symptoms in cancer patients." (PMID 41377804, 2025). "According to a recent review, 67 recognized natural compounds have the ability to fight cancer’s resistance to EGFR-TKIs through at least 30 pathways, primarily ROS, PD-L1, EGFR, MAPK, mTOR, HSP90, JNK, PTEN, and FOXO." (PMID 40728967, 2025). "The epidermal growth factor receptor (EGFR) plays a role in the development of various cancers, including NSCLC." (PMID 40104451, 2025). "Key signaling pathways governing cancer stemness, including the Wnt, Notch, and Hedgehog, are known to regulate resistance to EGFR-TKIs." (PMID 40533443, 2025). "EGFR is a commonly investigated target in cancer research due to its role in malignant cell transformation through abnormal activation or overexpression." (PMID 40356751, 2025). "Overall, this dual-model approach underscores the importance of incorporating 3D culture systems in preclinical cancer research and provides new insights into the regulatory roles of EGFR and IGF-IR in TNBC progression." (PMID 40943584, 2025). "Aptamer-functionalized exosomes targeting EGFR, nucleolin, or mucin-overexpressing cancer cells have shown high specificity and intracellular delivery of siRNA, as well as imaging agents in preclinical models." (PMID 41155971, 2025). "To evaluate the degradation efficiency of FolTAC v0.2 on single targets in cancers and immune-oncology, we engineered various FolTACs to target and degrade TfR1, EGFR, HER2, PD-L1, and VISTA." (PMID 41038820, 2025). "Epidermal growth factor receptor (EGFR) is a cell surface receptor, highly expressed in several cell types, especially in cancer cells." (PMID 40840553, 2025). "The findings indicated that the inhibition of the EGFR significantly reduced the migration of the cancer cells, and that subsequent stimulation with FXa was unable to reverse this effect." (PMID 40761247, 2025).
cancer (continued). "We demonstrate that, beyond targeting capabilities, bispecific DNA–peptide agents can also serve as platforms for payload delivery, enabling targeted cytotoxicity against cancer cells expressing EGFR and MET receptors." (PMID 41383748, 2025). "Although treatments targeting the EGFR, such as cetuximab, have demonstrated promise, the emergence of resistance in cancer cells, which typically occurs within 8–10 months of treatment initiation, hampers their effectiveness." (PMID 39823981, 2025). "Lipid reprogramming is closely linked to the epidermal growth factor receptor (EGFR) signaling pathway, which plays a crucial role in cancer development and progression." (PMID 40231255, 2025). "Small-molecule TKIs targeting the ATP-binding site of the EGFR tyrosine kinase domain are promising agents for cancer treatment." (PMID 40940907, 2025). "The use of EGFR inhibitors to treat cancer, such as gefitinib, lapatinib, and afatinib, has been recognized." (PMID 39898116, 2025). "The interaction between cancer cells and CAFs through paracrine signaling pathways contributes to treatment resistance, particularly resistance to EGFR TKIs, by activating the IGF-1R pathway and downstream EMT and stemness signaling." (PMID 39823981, 2025). "The epidermal growth factor receptor (EGFR), a member of the ERBB family of cell surface receptor tyrosine kinases, is implicated in cancer progression." (PMID 39944617, 2025). "EGFR inhibitors have been widely used to overcome EGFR-TKI resistance, while FASN, a key factor in cancer cell survival, has been linked to poor prognosis, recurrence risk, and drug resistance." (PMID 40872626, 2025). "Mutant EGFR mediates cancer cell evasion of immune control by reducing PD-L1 expression, inhibiting CD8+ T cell recruitment, and promoting Treg infiltration." (PMID 40165901, 2025). "Several studies highlighted the noticeable function of Anxa2 phosphorylation at Tyr23 in regulating cancer metastasis through its interaction with EGFR." (PMID 39912333, 2025). "EGFR is the most common antigen expressed on the surface of cancer cells, so EGFR-targeted NIR-PIT is now being successfully used for various types of tumors that express this antigen." (PMID 40574027, 2025). "In cancer therapy, EGFR (Epidermal Growth Factor Receptor) targeting operates by inhibiting the activity of EGFR mutants." (PMID 40822022, 2025). "Our method significantly improves the precision and reliability of EGFR-based cancer diagnostics by providing a computational framework for a morphology-induced measurement error correction." (PMID 41294763, 2025). "One of the most attractive targets for cancer therapy is the epidermal growth factor receptor (EGFR), which plays a crucial role in cell proliferation and survival and is often overexpressed in numerous cancers." (PMID 41583479, 2025). "EGFR signaling is crucial to cancer cell survival and progression, and its alteration or downregulation is associated with cytotoxicity, the induction of apoptosis, a anti-metastatic effect, and cancer cell death." (PMID 40863333, 2025). "In cancer cells co-cultured with M2, while p-EGFR was upregulated compared to A549 cells, EGFR expression levels were almost the same." (PMID 40076874, 2025). "By designing CAR-T cells to recognize and bind to EGFR on cancer cells, researchers can help convert cold tumors, which generally lack immune cell infiltration, into hot tumors that attract immune activity." (PMID 40281554, 2025). "Due to its significant role in cancer progression, EGFR is an important target for targeted cancer therapies." (PMID 40449599, 2025). "The growth inhibition of cancer cells after treatment with [225Ac]Ac-mcp-AB correlates with both the administered dose and the EGFR density in the cell types." (PMID 40536585, 2025). "The growth factors EGFR and VEGFR2 (epidermal growth factor receptor and vascular endothelial growth factor receptor 2) play significant roles in the genesis and progression of cancer." (PMID 41145684, 2025).